REN (renin)
Diseases named in the same sentence as REN in open-access papers (continued):
Sharing a sentence is not in itself a finding about the gene and the disease.
Hypertension (continued). "We speculated that an abnormal vascular structure and irregular renin localizations may be the cause of hypertension." (PMID 33546619, 2021). "Another important mechanism associated with hypertension development is the renin–angiotensin system (RAS), which may be found in a circulating form or as a specific tissue expression." (PMID 34630076, 2021). "Thus, increased renin secretion and associated hypertension have been observed in Cx40 knockout mice and mice with genetically engineered Cx45 reduction in JG cells." (PMID 33525532, 2021). "In Wilms tumor patients, high blood pressure has been suggested to be the result of activation of the renin-angiotensin-aldosterone system, suggesting there might be a higher risk of hypertension in patients with bilateral Wilms tumors." (PMID 34884260, 2021). "Vitamin D has also been associated with hypertension and can impact the renin-angiotensin system." (PMID 34452063, 2021). "Moreover, thiamin deficiency contributes to vascular dysfunction and hypertension respectively via reduction of nitric oxide production and up-regulation of mRNAs implicated in the renin-angiotensin system." (PMID 33995940, 2021). "The activation of the renin-angiotensin-aldosterone system (RAAS) occurs in progressive kidney disease leading to hypertension, which develops before the loss of kidney function and is an important risk factor for progression to ESRD, cardiovascular morbidity and mortality." (PMID 34206927, 2021). "Likewise, to a lesser extent, we show that carriers of another hypertension-predisposing SNP, REN rs12750834, can also portend a higher risk of BC, while carriers of the AT2R rs11091046 are protected." (PMID 34898568, 2021). "The sympathetic nervous system over-activation, stimulation of the renin–angiotensin–aldosterone system, alterations in adipose-derived cytokines, insulin resistance, and structural and functional renal changes are implicated in obesity–hypertension complex." (PMID 34442101, 2021). "Whether abnormalities in Stox1-KO placentas arose as a direct consequence of STOX1 deficiency, or secondary to renin-induced hypertension or other pathophysiology, is uncertain." (PMID 33301424, 2021). "In addition to microbiota dysbiosis, nitric oxide (NO) deficiency and the aberrant renin–angiotensin system (RAS) have been associated with hypertension of developmental origins." (PMID 33800916, 2021). "Moreover, minocycline- and HF-induced hypertension, individually or together, is associated with the aberrant activation of the renin–angiotensin system (RAS)." (PMID 33800916, 2021). "The renin-angiotensin-aldosterone system (RAAS) is implicated in hypertension and kidney disease." (PMID 33669059, 2021). "Additionally, Vitamin D deficiency increases the risk of cardiovascular disease by activating the renin–angiotensin system, leading to hypertension." (PMID 34473410, 2021). "Among different Cxs, Cx40-/- mice had hypertension associated with high plasma renin activity." (PMID 33525532, 2021). "Since the REN gene is an attractive genetic marker candidate for hypertension associated disease, the REN rs5707 polymorphism has been studied in the development of coronary artery disease and preeclampsia, but those studies did not reveal a significant relationship." (PMID 34945850, 2021). "More licorice intake may cause hypertension, water retention, sodium, hypokalemia, and suppress renin-aldosterone." (PMID 34961221, 2021). "Moreover, low renin has been associated with cardiovascular risk in patients with “essential hypertension” and it has been shown to be a predictor of blood pressure response to MRAs in this population." (PMID 33841329, 2021). "Hypertension in JGCT is caused by high renin and hyperaldosteronism." (PMID 32441904, 2020). "Moreover, global deletion of the ER stress chaperone Ddit3 (CHOP) prevents vitamin D-deficiency-induced renin-dependent hypertension in mice, and their macrophages are unable to activate JG cell renin production." (PMID 32968066, 2020).
Hypertension (continued). "Hypertension studied as a host risk factor for Covid-19 may underscore the involvement of the renin-angiotensin system (RAS) in the pathogenesis of the disease." (PMID 33320875, 2020). "Furthermore, the Arc has been proposed as a potential region in which the leptin-melanocortin and renin-angiotensin-aldosterone systems interact to control sympathetic nerve activity, relevant to obesity-associated arterial hypertension." (PMID 32720895, 2020). "This may be due to the effect of high-salt diets on the function of the renin-angiotensin system that causes fluid retention which increases the cardiac burden and uncontrolled hypertension." (PMID 32952831, 2020). "As it is indicated in different literature, the association between obesity and hypertension is related to insulin resistance, sodium retention, increased sympathetic nervous system activity, activation of renin–angiotensin–aldosterone, and altered vascular function." (PMID 32957951, 2020). "Some studies have found that exposure to protease inhibitors, especially lopinavir/ritonavir, is associated with development of hypertension, which may be attributable to activation of the adipocyte renin-angiotensin system." (PMID 32487185, 2020). "The subset phenotype of low-renin hypertension, which is also associated with salt sensitivity and diuretics, is more prevalent as age increases, which could also partly contribute to our findings." (PMID 32645850, 2020). "TyG index has been associated with incident hypertension in a Chinese population, possibly due to insulin resistance-related hyperinsulinemia and a subsequent increase in sympathetic nervous system activity and renin-angiotensin-aldosterone system activation." (PMID 33322810, 2020). "These rare tumors hypersecrete renin and cause high blood pressure in adolescents and young adults." (PMID 32433950, 2020). "It should also be considered, however, that a particular pathway sensitive to TZD inhibition, e.g., renin–angiotensin II, could underlie the multiple types of hypertension associated with responders (Guiding Parameters (a) Therapeutic TZD dose/concentration)." (PMID 31543812, 2019). "Hyponatremic hypertensive syndrome, a disorder of severe hypertension and hyponatremia, could result from any causes of high renin conditions." (PMID 30791890, 2019). "Overexpression of renin in the collecting duct caused spontaneous hypertension." (PMID 31546789, 2019). "High renin hypertensive individuals are often considered to have vasoconstriction-dependent hypertension, with an increased peripheral resistance, whereas hypertension due to primary hyperaldosteronism may be associated with low renin levels." (PMID 31581667, 2019). "This reduction may be due to population-wide improved management of diabetes and hypertension, and the associated increased use of renin-angiotensin-blocking medications in the UK since the early 2000s." (PMID 31693662, 2019). "Fourth, visceral fat may be associated with activation of the renin-angiotensin-aldosterone system which has been implicated in obesity-associated hypertension." (PMID 31320919, 2019). "We speculated that miso with potent ACE inhibitory activity attenuates hypertension to a greater extent than regular commercially available miso, particularly hypertension associated with enhancement of the renin–angiotensin system (RAS)." (PMID 30631160, 2019). "More than 150 genes have been linked to hypertension and genetic risk factors appear to vary with time and study population, the genes encoding the proteins involved in the renin-angiotensin-aldosterone system (RAAS) consistently appear to be key factors in hypertension." (PMID 31484569, 2019). "Activation of ENaC, either due to structural variants of the channel subunits (e.g.,: SCNN1B) or altered activity of regulatory processes (including NEED4), could underlie low-renin hypertension in African Americans." (PMID 30832344, 2019).
Hypertension (continued). "Accordingly, VDR-deficient mice display high renin and AngII levels and develop hypertension." (PMID 31623356, 2019). "Alternatively, a particular pathway sensitive to TZD inhibition, e.g., renin–angiotensin II, could underlie the multiple types of hypertension associated with responders." (PMID 31543812, 2019). "By stimulating the renin- angiotensin system, reducing nitric oxide (NO) release from endothelial cells and inhibiting NO synthase 1 uric acid causes renal vasoconstriction and leads to renal ischemia and hypertension." (PMID 29973162, 2018). "Activation of the renin-angiotensin system (RAS) is associated with hypertension and heart disease." (PMID 29895976, 2018). "Also, as inhibitors of ACE and renin, they can be further investigated as natural agents for managing hypertension, which is a strong risk factor for stroke." (PMID 30349677, 2018). "In addition, ablation of Cx40 is also associated with a decrease in Cx37 expression and the development of a hypertension caused by a dysregulation of renin production." (PMID 29874791, 2018). "To date, there is evidence supporting a disordered renin–angiotensin aldosterone system, altered calcium and phosphate metabolism (causing high levels of fibroblast growth factor 23 and parathyroid hormone) and hypertension." (PMID 29024966, 2018). "In particular, inverse relationship between magnesium levels and systolic and diastolic pressure values and risk of death from hypertension have been reported, in line with a similar inverse relationship between Mg2+ levels and circulating renin concentrations and stiffened blood vessels." (PMID 29992053, 2018). "Previous studies have showed that arterial hypertension associated to renal nerve hyperactivity may involve alterations in tubular sodium reabsorption, arteriolar resistance and renin release." (PMID 28632750, 2017). "It has been proposed that a triangular pattern of positive feedback—with vertices representing autonomic nervous system (ANS) activity, systemic inflammation (INF), and renin-angiotensin system (RAS) signaling—underlies the pathogenesis of cardiovascular dysfunction in hypertension." (PMID 28732007, 2017). "Hypertension is a leading cause of HF and exerts a deleterious effect on the cardiovascular system through direct haemodynamic mechanisms and also through overactivation of the renin-angiotensin-aldosterone system (RAAS)." (PMID 28707261, 2017). "Genetic risk factors such as gene polymorphisms of the angiotensinogen-converting enzyme and of the renin-angiotensin-aldosterone system, could cause myocardial infarction, hypertension, and cardiovascular complications." (PMID 28052754, 2017). "For instance, in Liddle’s syndrome (an autosomal dominant condition with hypertension associated with suppressed aldosterone and renin levels), a mutation in the epithelial Na+ channel gene induces increased rates of Na+ reabsorption, volume expansion, and hypertension." (PMID 29109301, 2017). "Importantly, polymorphisms in the renin–angiotensin system (RAS) genes have already linked the hypertension aspect of renal diseases to IgAN73." (PMID 28831120, 2017). "Specifically, molecules of the renin-angiotensin-aldosterone system not only play important roles in the control of blood pressure, but they are also associated with the genesis of arterial hypertension, thus constituting a need for pharmacological interventions." (PMID 27347925, 2016). "Third, CI-AKI is associated with a renal insufficiency and hypertension secondary to renin-dependent hypertension in the CKD model and in the chronic hyperglycemia model it results in increased renal plasmatic flow, glomerular hyperfiltration, and hyperosmolar urine." (PMID 27034930, 2016). "Hypertension may primarily be caused by fluid overload, as indicated by a suppressed renin–angiotensin–aldosterone system and enhanced atrial natriuretic peptide release." (PMID 27632175, 2016).
Hypertension (continued). "A Cx43 knock-in mouse strain by Cx32 remains normotensive in a 2-kidney and 1-clip model associated with a lower level of renin, indicating that Cx43 may mediate hypertension via renin in that model." (PMID 27064407, 2016). "Similarly, Feig and Johnson suggested that early hypertension is associated with high serum uric acid and high serum renin levels, leading to higher responsiveness to RAS blockers." (PMID 27428212, 2016). "Inhibition of renin release into the bloodstream was associated with hypertension." (PMID 27805066, 2016). "Second, oxidative stress and the renin-angiotensin system are common mechanisms that contribute to both PD and hypertension, which may mediate the association between the two diseases." (PMID 27906991, 2016). "The fact that renin gene transcription is regulated by WT-1, and that inherited mutations in the WT-1 gene can lead to hypertension, may explain the findings of patients with high renin and hypertension." (PMID 27009470, 2016). "However, elucidating the homeostatic effects of altered gene function is not always straightforward, as exemplified by the mRen2 rat, which overexpresses the mouse renin (Ren2) gene, causing severe hypertension." (PMID 27935823, 2016). "To address whether the severe colitic phenotype of RenTg mice is caused by renin overproduction or by high blood pressure, we treated RenTg mice with renin inhibitor aliskiren or hydralazine, a vasodilator." (PMID 27271344, 2016). "Molecular variants of the renin gene thought to be a genetic risk factor may be involved in the etiology of hypertension." (PMID 26090220, 2015). "However, the patient was also evaluated for all other possible causes of secondary hypertension, thus discovering renin-dependent hyperaldosteronism." (PMID 26084817, 2015). "On the other hand they suggested that -5312, -5434, and A BglI G polymorphisms of renin gene might play an important role in the occurrence of arterial hypertension (AH)." (PMID 26090220, 2015). "Reninoma is a rare juxtaglomerular cell tumor causing renin-mediated hypertension." (PMID 26084817, 2015). "The resistance of hypertension‐associated atrial fibrosis to the AT1 receptor antagonist may provide insight into the basis to the ineffectiveness of drugs targeting the renin–angiotensin system in reducing incidence of AF in hypertensive patients." (PMID 25626873, 2015). "Primary aldosteronism is an endocrine disorder that is associated with hypertension, hypokalemia, metabolic alkalosis, suppressed plasma renin, and inappropriately elevated aldosterone secretion that is caused by an adrenal adenoma or bilateral adrenal hyperplasia." (PMID 25352832, 2014). "Third, only six common polymorphisms were examined in AGTRL1 gene, and it is highly encouraged to incorporate other polymorphisms, especially the low-penetrance polymorphisms in this gene or other validated hypertension-susceptibility genes, such as renin-angiotensin system genes." (PMID 24465893, 2014). "Medical imaging looking for more common causes of renin-mediated hypertension, such as renovascular or renal parenchymal disease, might miss these small tumors." (PMID 25177679, 2014). "In addition, older age, lower initial GFR, history of diabetes, history of hypertension and preoperative renin angiotensin blockade were associated with AKIN stage 1 (data not shown)." (PMID 25394836, 2014). "Here, we have studied whether microglia are activated within cardiovascular regulatory area(s) of the brain during hypertension, especially in high blood pressure that is associated with chronic activation of the renin-angiotensin-system." (PMID 25302502, 2014). "However, the vascular remodeling (structural changes) in hypertension is also associated with activation of the renin-angiotensin system, endothelin-1, endothelial dysfunction, oxidative stress, and ADMA." (PMID 24795884, 2014). "Reninomas (juxtaglomerular cell tumors) are a very rare cause of renin-mediated hypertension." (PMID 25177679, 2014).
Hypertension (continued). "Reninoma (juxtaglomerular cell tumor) is a rare cause of renin-mediated hypertension." (PMID 25177679, 2014). "High renin and high aldosterone combined with a normal renin/aldosterone ratio are suggestive of normal, albeit excessive, secretion of both hormones typical of the renal causes of hypertension (RAS, renal parenchymal disease, or reninoma)." (PMID 25177679, 2014). "Mitochondrial dysfunction is implicated in many cardiovascular diseases, including hypertension, and may be associated with an overactive renin-angiotensin system (RAS)." (PMID 23401750, 2013). "Overexpression of AR-1 activates the renin-angiotensin-aldosterone system and causes hypertension." (PMID 23978069, 2013). "The associations between obesity, hypertension and diabetes are well established, and the renin-angiotensin system (RAS) may provide a link among them." (PMID 23894285, 2013). "The present paper discusses evidence in support of the concept that the brain renin-angiotensin system (RAS) might be linked to sympathetic nerve activity in hypertension." (PMID 23227311, 2012). "Several studies have shown that activation of the renin-angiotensin system may lead to hypertension, a major risk factor for the development of chronic kidney disease (CKD)." (PMID 23300650, 2012). "However, a recently published study found 25-hydroxyvitamin D to be associated with plasma renin activity and with salt-sensitivity in patients with low-renin hypertension in 223 Caucasian hypertensive patients." (PMID 23049672, 2011). "Inflammation may be associated with hypertension and the development and progression of renal dysfunction through activation of the renin-angiotensin system and its influence on endothelial function." (PMID 20078870, 2010). "Genome-wide linkage, association, and candidate gene studies in patients and animal hypertension models have identified an array of associated variants for hypertension that include sodium channels, the sympathetic nervous system and adrenergic pathways, and the renin-angiotensin-aldosterone system." (PMID 20886000, 2010). "This increase might be related to the relatively high use of thiazides in association with renin-angiotensin antagonists in patients with hypertension in our country, particularly given that both kinds of drugs have been associated with improvements in BMD." (PMID 20331862, 2010). "Renin-angiotensin mechanisms underlie sugar-induced hypertension in many animal models." (PMID 20804606, 2010). "We have previously shown a relationship of the R563Q mutation of the SCNN1b gene with hypertension, but the prevalence of this SNP in the hypertensive population is 5% and <1% in normotensives and cannot account for the suppressed plasma renin activity in 70% of indigenous Africans." (PMID 20886000, 2010). "It is associated with increased vascular permeability, activation of coagulation cascade, and renin secretion, which may lead to the acute renal failure typically associated with accelerated hypertension." (PMID 20981312, 2010). "Histopathologically there is concentric edematous intimal thickening of interlobular arteries and fibrinoid arteriolar necrosis causing elevation of plasma renin level with onset or aggravation of hypertension and rapid deterioration of renal function as a result of ischemic glomerulopathy." (PMID 18474117, 2008). "Furthermore, there remains some debate about the true distinction between genuine autonomous primary aldosteronism and relative aldosterone excess association with low renin hypertension." (PMID 17490489, 2007). "Accordingly, the βENaC G589S could confer some susceptibility to low-renin hypertension, but more data on untreated patients and families are needed." (PMID 15661075, 2005). "Additionally, high salt and fat intake may exacerbate hypertension risk by affecting vascular function and the renin-angiotensin system." (PMID 40647264, 2025).